TBP (TATA-box binding protein)
Description:
The TFIID basal transcription factor complex plays a major role in the initiation of RNA polymerase II (Pol II)-dependent transcription. TFIID recognizes and binds promoters with or without a TATA box via its subunit TBP, a TATA-box-binding protein, and promotes assembly of the pre-initiation complex (PIC). The TFIID complex consists of TBP and TBP-associated factors (TAFs), including TAF1, TAF2, TAF3, TAF4, TAF5, TAF6, TAF7, TAF8, TAF9, TAF10, TAF11, TAF12 and TAF13. The TFIID complex structure can be divided into 3 modules TFIID-A, TFIID-B, and TFIID-C. TBP forms the TFIID-A module together with TAF3 and TAF5. TBP is a general transcription factor that functions at the core of the TFIID complex. During assembly of the core PIC on the promoter, as part of TFIID, TBP binds to and also bends promoter DNA, irrespective of whether the promoter contains a TATA box. Component of a BRF2-containing transcription factor complex that regulates transcription mediated by RNA polymerase III. Component of the transcription factor SL1/TIF-IB complex, which is involved in the assembly of the PIC during RNA polymerase I-dependent transcription. The rate of PIC formation probably is primarily dependent on the rate of association of SL1 with the rDNA promoter. SL1 is involved in stabilization of nucleolar transcription factor 1/UBTF on rDNA.
Synonyms: GTF2D1; TFIID; TBP1; GTF2D; HDL4; SCA17
Tractability: Small molecule: a structure with a bound ligand is known. PROTAC: ubiquitination databases record sites on it.
Gene: Protein-coding gene on chromosome 6 (170,554,302 to 170,572,870, forward strand). Ensembl gene ENSG00000112592.
Subcellular location: Nucleus
Subcellular location (Human Protein Atlas): Nucleoplasm; Cytosol
Pathways (Reactome):
Gene expression (Transcription): B-WICH complex positively regulates rRNA expression; NoRC negatively regulates rRNA expression; RNA Polymerase I Promoter Escape; RNA Polymerase I Transcription Initiation; RNA Polymerase I Transcription Termination; RNA Polymerase II Pre-transcription Events; RNA Polymerase II Promoter Escape; RNA Polymerase II Transcription Initiation; RNA Polymerase II Transcription Initiation And Promoter Clearance; RNA Polymerase II Transcription Pre-Initiation And Promoter Opening; RNA Polymerase III Abortive And Retractive Initiation; RNA Polymerase III Transcription Initiation From Type 1 Promoter; RNA Polymerase III Transcription Initiation From Type 2 Promoter; RNA Polymerase III Transcription Initiation From Type 3 Promoter; RNA polymerase II transcribes snRNA genes; SIRT1 negatively regulates rRNA expression
Disease: HIV Transcription Initiation; RNA Polymerase II HIV Promoter Escape; Transcription of the HIV genome
Signal Transduction: Estrogen-dependent gene expression
Gene Ontology:
Molecular function: aryl hydrocarbon receptor binding; core promoter sequence-specific DNA binding; DNA-binding transcription factor binding; enzyme binding; protein binding; RNA polymerase I core promoter sequence-specific DNA binding; RNA polymerase II core promoter sequence-specific DNA binding; RNA polymerase II general transcription initiation factor activity; RNA polymerase II general transcription initiation factor binding; RNA polymerase III general transcription initiation factor activity; TFIIB-class transcription factor binding; transcription cis-regulatory region binding; DNA binding; RNA polymerase II-specific DNA-binding transcription factor binding
Biological process: mRNA transcription by RNA polymerase II; positive regulation of transcription by RNA polymerase III; positive regulation of transcription initiation by RNA polymerase II; regulation of DNA-templated transcription; RNA polymerase II preinitiation complex assembly; transcription by RNA polymerase II; transcription by RNA polymerase III; transcription initiation at RNA polymerase II promoter; DNA-templated transcription initiation; RNA polymerase I preinitiation complex assembly
Cellular component: chromatin; euchromatin; nucleoplasm; nucleus; protein-containing complex; RNA polymerase II transcription regulator complex; RNA polymerase transcription factor SL1 complex; transcription factor TFIIA complex; transcription factor TFIID complex; transcription factor TFIIIB complex; cytoplasm; female pronucleus; male pronucleus; pronucleus
Genetic constraint (gnomAD): Loss-of-function variants: 8 observed, 35.19 expected, observed/expected ratio (o/e) 0.23, 90% interval 0.13 to 0.41. The upper end of that interval is the gene's LOEUF score, 0.41, which puts it in group 1 of 6, group 1 being the genes least tolerant of losing a copy. Missense variants: 197 observed, 339.81 expected, observed/expected ratio (o/e) 0.58, 90% interval 0.51 to 0.65. Synonymous variants: 132 observed, 120.19 expected, observed/expected ratio (o/e) 1.1, 90% interval 0.95 to 1.27.
Homologues: Orthologues: chimpanzee TBP (99% identical), macaque TBP (96% identical), rabbit TBP (93% identical), dog TBP (93% identical), guinea pig TBP (91% identical), mouse Tbp (91% identical), rat Tbp (86% identical), tropical clawed frog tbp (83% identical), zebrafish tbp (81% identical). Paralogues in human: TBPL2 (60% identical), TBPL1 (22% identical).
Diseases named in the same sentence as TBP in open-access papers:
TBP is named in the same sentence as 145 diseases in open-access papers, as found by Europe PMC text mining. Sharing a sentence is not in itself a finding about the gene and the disease. The quoted sentences say what the papers report.
spinocerebellar ataxia type 17 (36 papers, 2005 to 2025). A rare subtype of type I autosomal dominant cerebellar ataxia (ADCA type I). "Expansion of the CAG/CAA repeat located in exon 3 of TBP causes spinocerebellar ataxia type 17 (SCA17), typically when allele size falls in the range of 46-55x." (PMID 39775235, 2024). "Polyglutamine expansion in the TBP can cause spinocerebellar ataxia type 17, which prompted us to further investigate the relationship between these target genes and LID in future studies." (PMID 36138942, 2022). "Spinocerebellar ataxia type 17 (SCA17) is caused by the expansion of a CAG trinucleotide (42 or more repeats) in the TATA-box-binding protein gene (TBP)." (PMID 33733696, 2021). "Recently, mutations in the TATA-box-binding gene (TBP), normally associated with spinocerebellar ataxia 17 (SCA17), were identified in a patient with FTD whose MRI showed cerebellar atrophy." (PMID 32733193, 2020). "Spinocerebellar ataxia type 17 (SCA17) is caused by a CAG/CAA expansion mutation encoding an expanded polyglutamine (polyQ) tract in TATA-box binding protein (TBP), a general transcription initiation factor." (PMID 32377295, 2020). "Spinocerebellar ataxias 17 (SCA17) is caused by polyglutamine (polyQ) expansion in the TATA box-binding protein (TBP)." (PMID 32107387, 2020). "Spinocerebellar ataxia 17 (SCA 17) is a rare form of autosomal dominant cerebellar ataxia (ADCA) caused by a coding CAG/CAA expansion in TBP, the gene for TATA-binding protein." (PMID 25349749, 2014). "Spinocerebellar ataxia 17 (SCA 17) is a rare autosomal dominant cerebellar ataxia (ADCA) caused by a CAG/CAA expansion in the TBP gene, reported from a limited number of countries." (PMID 25349749, 2014). "Spinocerebellar ataxia 17 (SCA17) is caused by expansion of the polyglutamine (polyQ) tract in human TATA-box binding protein (TBP) that is ubiquitously expressed in both central nervous system and peripheral tissues." (PMID 22530004, 2012). "Finally, SCA17, also known as Huntington disease-like 4 (HDL4), is caused by an expansion of the TATA box-binding protein (TBP) gene, which encodes for a protein involved in gene transcription." (PMID 37698771, 2024). "For example, spinocerebellar ataxia 17 is an inherited progressive movement disorder primarily affecting the cerebellum, which is caused by an expanded polyglutamine tract in TBP, altering its interaction with TFIID and dysregulating expression of its target genes." (PMID 39323550, 2024). "HDL4, also classified as spinocerebellar ataxia type 17 (SCA17), is an autosomal dominant disorder caused by trinucleotide repeats expansion in the TATA-box-binding protein (TBP) gene located on chromosome 6q27." (PMID 38921008, 2024). "Spinocerebellar ataxia type 17 (SCA17) is caused by CAG/CAA polyglutamine repeats in the TATA-binding protein (TBP)." (PMID 33671313, 2021). "Spinocerebellar ataxia type 17 (SCA17) is a rare autosomal dominant neurodegenerative disease caused by a CAG repeat expansion in the TATA-box binding protein gene (TBP)." (PMID 30532692, 2018). "The last of the known polyglutamine diseases is Spinocerebellar Ataxia Type 17 (SCA17), which is caused by CAG or CAA repeat expansions of 45 or more within the TBP gene." (PMID 38921455, 2024). "The aim of this paper is to conduct a comparative analysis of the repeat region of the TBP gene (OMIM: 600075), where a dynamic mutation causes spinocerebellar ataxia type 17 (SCA17; OMIM: 607136)." (PMID 39125760, 2024). "On the clinical suspicion of an HD phenocopy, we performed analysis of TBP and ATN1, respectively, associated with spinocerebellar ataxia type 17 and dentatorubral‐pallidoluysian atrophy." (PMID 36237940, 2022). "Spinocerebellar ataxia type 17 (SCA17) is a neurodegenerative disease caused by a polyglutamine-encoding trinucleotide repeat expansion in the gene of transcription factor TATA box-binding protein (TBP)." (PMID 35482253, 2022).
spinocerebellar ataxia type 17 (continued). "Spinocerebellar ataxia type 17 (SCA17) is an autosomal dominant ataxia caused by an expanded polyglutamine (polyQ) in a general transcription initiation factor, the TATA-box binding protein (TBP)." (PMID 22530004, 2012). "Spinocerebellar ataxia type 17 (SCA17), a neurodegenerative disorder in man, is caused by an expanded polymorphic polyglutamine-encoding trinucleotide repeat in the gene for TATA-box binding protein (TBP), a main transcription factor." (PMID 15989694, 2005). "Spinocerebellar Ataxia Type 17 (SCA17) is the most recently discovered member of the polyQ disease family, resulting from CAG/CAA expansion in the gene that encodes the TATA box-binding protein (TBP), an essential player in the basal transcriptional machinery of all eukaryotes." (PMID 37551423, 2023). "The TATA box-binding protein (TBP), which contributes to the SL1 complex, has been linked to spinocerebellar ataxia type 17 (SCA17)." (PMID 38791054, 2024). "Spinocerebellar ataxia type 17 (SCA17; OMIM #607136) is a rare autosomal dominant neurodegenerative disorder caused by a CAG repeat expansion in exon 3 of the TBP that ultimately results in a loss of coordination and balance." (PMID 30532692, 2018). "Spinocerebellar ataxia type 17 (SCA17) involves the expression of a polyglutamine (polyQ) expanded TATA-binding protein (TBP), a general transcription initiation factor." (PMID 25549101, 2014). "Huntington's disease, spinal and bulbar muscular atrophy, and spinocerebellar ataxia 17 (SCA17) are caused by expansions in the polyglutamine (polyQ) repeats in Huntingtin protein (Htt), androgen receptor protein (AR), and TATA-binding protein (TBP), respectively." (PMID 17868456, 2007). "It is not yet clear how ubiquitously-expressed proteins can cause the selective degeneration of particular populations of neurons, such as in spinocerebellar ataxia type 17, SCA17, which results from a CAG trinucleotide repeat expansion in the ubiquitously expressed transcription factor TBP." (PMID 32107387, 2020). "Spinocerebellar Ataxia Type 17 (SCA17) is the most recently identified member of the polyglutamine (polyQ) family of disorders, resulting from abnormal CAG/CAA expansion in the TATA box-binding protein (TBP), an initiation factor essential for of all eukaryotic transcription." (PMID 37551423, 2023).
dentatorubral-pallidoluysian atrophy (33 papers, 2007 to 2025). Dentatorubral pallidoluysian atrophy (DRPLA) is a rare subtype of type I autosomal dominant cerebellar ataxia (ADCA type I). "For ataxias SCA1, SCA2, SCA3, SCA6, SCA7, SCA17 and dentatorubral-pallidoluysian atrophy, expansion beyond 39, 33, 45, 20, 34, 41, and 35 repeats in the ATXN1, ATXN2, ATXN3, CACNA1A, ATXN7, TBP, and ATN1 genes, respectively, will cause disease." (PMID 35592702, 2022). "TBP is an important general transcription factor that also plays a role in the mechanism of other polyQ disorders (SCA1, SCA2, SCA3, Huntington’s disease, and dentatorubral-pallidoluysian atrophy) by sequestering in the polyQ-pathological aggregates of those diseases." (PMID 39456985, 2024).
Ataxia (32 papers, 2005 to 2026). Ataxia refers to impaired coordination of voluntary muscle movement. "The target genes of rno-miR-298-5p, including PCP4 and TBP, are associated with some movement abnormality disorders such as Huntington’s disease and spinocerebellar ataxia." (PMID 36138942, 2022). "Unless SCA17 is a rare type of dominantly inherited ataxia, the repeat expansion within the TBP gene arose at unrelated genotypes." (PMID 15989694, 2005). "A CAG repeat expansion in the TATA-box-binding protein (TBP) gene on chromosome 6 has been identified as the cause of SCA17 in some familial and sporadic cases, resulting in cerebellar ataxia and followed by dementia, parkinsonism, and dystonia, with onset in childhood and adulthood." (PMID 36140389, 2022). "Ataxia patients with only 41 repeats of the TBP gene have also been reported." (PMID 25866756, 2015). "The frequency is followed by ATXN7: 6.09%, TBP: 5.59%, ATXN2: 5.03%, CACNA1A: 4.28%, PPP2R2B: 2.68%, and ATXN3: 2.42% with respective cutoff values in uncharacterized ataxia cases." (PMID 36618024, 2022).
Huntington disease (29 papers, 2007 to 2024). Huntington disease (HD) is a rare neurodegenerative disorder of the central nervous system characterized by unwanted choreatic movements, behavioral and psychiatric disturbances and dementia. "Recent studies have highlighted that mutations and aggregation of transcription factors such as TATA-binding protein (TBP), a component of the RNA polymerase II pre-initiation complex, are associated with Huntington’s disease." (PMID 38002524, 2023). "It is also implicated in other neurodegenerative diseases like Huntington’s disease, since the protein aggregates formed in such diseases also contain TBP." (PMID 28774347, 2017). "SCA 17, also called Huntington’s disease-like-4 because of the similarity in its symptomatology with Huntington’s disease (HD), is caused by a CAG expansion in the coding region of the TATA box-binding protein (TBP) gene." (PMID 38391932, 2024). "TBP, a general transcription factor, has been found in the nuclear aggregates in postmortem brain tissue of patients of Huntington’s disease (HD) and Spinocerebellar ataxias like (SCA1, SCA2, and SCA3)." (PMID 28774347, 2017). "Expanded trinucleotide repeat sequences in TBP have been shown to cause spinocerebellar ataxia-17 (SCA17) and to phenocopy Huntington's disease." (PMID 26769797, 2016). "Besides, SCA17, caused by the expansion of polyQ tract in the TATA binding protein itself, normal TBP is also found in intra nuclear protein aggregates formed in other neurodegenerative diseases, notably, huntington's disease." (PMID 18000542, 2007). "TBP, GRM5, and GRIA1 were co-enriched in Huntington’s disease pathway." (PMID 36561136, 2022).
Parkinsonism (15 papers, 2012 to 2025). Characteristic neurologic anomaly resulting from degeneration of dopamine-generating cells in the substantia nigra, a region of the midbrain, characterized clinically by shaking, rigidity, slowness of movement and difficulty with walking and gait. "ATXN2 and TBP were also associated with susceptibility to Parkinson disease, a common neurological disorder, while ATXN2 was also associated with susceptibility to amyotrophic lateral sclerosis (ALS), a neurodegenerative disease." (PMID 41254939, 2025). "Diverse phenotypes resembling both HD, Alzheimer’s disease and Parkinson’s disease have previously been reported in patients with short expansions in the TBP gene." (PMID 22889412, 2012). "The genetic markers of Parkinson’s disease BCL2, TBP,and TAF1 exert greater regulatory influence on acylcarnitinemetabolism enzymes, while PARP1 equally affects enzymesinvolved in both amino acid and acylcarnitine metabolism." (PMID 39944797, 2024).
Machado-Joseph disease (11 papers, 2007 to 2025). "The most frequent SCA worldwide are those caused by CAG repeat expansions, as SCA1 (in ATXN1), DRPLA (ATN1), SCA2 (ATXN2), Machado-Joseph disease (MJD)/ SCA3 (ATXN3), SCA6 (CACNA1A), SCA7 (ATXN7), and SCA17 (TBP), usually designated polyglutamine (polyQ) ataxias." (PMID 39048885, 2024).
breast carcinoma (9 papers, 2008 to 2025). "We used RT-qPCR to determine RG candidate levels in normoxic breast cancer cells, removing TBP and EPAS1 from downstream analysis due to insufficient transcript abundance." (PMID 39838295, 2025). "We next sorted the RNASeq data of primary breast cancer patients based on RESTlow and RESThigh groups with 300 patients for each group and examined the expression patterns of TBP, CEBPB, REST, CTCF, RAD21 and SMC3 in addition to unsorted patient dataset." (PMID 30335837, 2018). "Previous studies have recommended SFRS4 and TBP as the reference genes in HCV-induced HCC or breast carcinomas." (PMID 29180379, 2017). "Distant metastases were observed in the lungs of both TP (4 of 14 cases) and TBP (3 of 6 cases) mice, which is noteworthy because relatively few transgenic mammary tumor models metastasize." (PMID 23173005, 2012). "However, GAPDH and TBP in hepatic cancer cell lines and ACTB and B2M in breast cancer cell lines have M values > 1, which causes us to consider them as unstable reference genes." (PMID 34752497, 2021). "RPLPO and TBP also belonged to one of the most stably expressed genes in breast carcinomas." (PMID 24001041, 2013). "Conclusively, we identified multiple genes, including DIS3, TBP, and EXOC1, as potential dual-effectors that regulate both MHC-I expression and cell survival in breast cancer." (PMID 39408874, 2024). "Further flow cytometry experiments confirmed that knockout of DIS3, TBP, or EXOC1 individually markedly increased MHC-I levels on the cell surface of breast cancer MCF7 cells." (PMID 39408874, 2024). "The efficiency and specificity of these primers except hypoxanthine phosphoribosyltransferase 1 (HPRT1), TATA-box binding protein (TBP), and actin beta (ACTB) were also studied in exosomal RNA of hepatic and breast cancer cell lines by our team recently." (PMID 34752497, 2021). "In breast cancer cell lines, GAPDH, TBP, and UBC were the most stable reference genes almost equally." (PMID 34752497, 2021). "While TBP (mean Cq ± SD = 29 ± 2.59) and HPRT1 (mean Cq ± SD = 25.36 ± 1.311) were the least abundant reference genes in hepatic and breast cancer cell lines, respectively." (PMID 34752497, 2021). "When examining the 18 patient tissue specimens (ER+/ER- IBC/normal) or the breast cancer tissue specimens alone (ER+/ER- IBC), the 3-gene combination of RPLP0, TBP and PUM1 were consistently identified by geNorm to exhibit the highest degree of stability." (PMID 18211679, 2008). "Moreover, similar to the geNorm output, TBP, and GAPDH for hepatic cancer cell lines and B2M for breast cancer cell lines were sorted as the least stable reference genes." (PMID 34752497, 2021). "Furthermore, we verified partially according to KEGG functional enrichment or gene-dependency analysis and figured out multiple genes, including PIP5K1A, NCKAP1, CYFIP1, DIS3, TBP, and EXOC1, as effective gene targets for increasing MHC-I expression in breast cancer." (PMID 39408874, 2024).